FTH1 (ferritin heavy chain 1)
Diseases named in the same sentence as FTH1 in open-access papers (continued):
Sharing a sentence is not in itself a finding about the gene and the disease.
epilepsy (3 papers, 2021 to 2026). A brain disorder characterized by episodes of abnormally increased neuronal discharge resulting in transient episodes of sensory or motor neurological dysfunction, or psychic dysfunction. "To investigate whether dysregulation of iron metabolism occurs in GD-induced epilepsy and the effects of iNOS inhibition, we evaluated the levels of ferritin (FTH-1), an iron-storage protein, at 3.5 months post GD intoxication." (PMID 38129129, 2024). "Here, FTH-1 upregulation was detected also after the development of SRS, when neuronal loss is minimal, implicating altered iron metabolism in the pathogenesis and progression of epilepsy." (PMID 34292399, 2021). "We identify and validate ferroptosis-related genes (e.g., FTH1, FTL, PCBP1) as potential biomarkers and therapeutic targets, supported by congruent biochemical evidence of oxidative stress in this drug-resistant epilepsy." (PMID 42051157, 2026).
Granuloma (3 papers, 2017 to 2023). A compact, organized collection of mature mononuclear phagocytes, which may be but is not necessarily accompanied by accessory features such as necrosis. "Fth1−/− mice tended to have a lower percentage of tissue area occupied by granulomas, as compared to Fth1+/+ mice (39.8 ± 10.4% vs. 50.3 ± 13.3%), consistent with a decreased inflammatory response." (PMID 35008695, 2021). "In contrast, the percentages of FTH1-positive macrophages were significantly higher in the diagnostic biopsy specimens than in the therapeutic resection tissues in non-necrotizing and necrotizing granulomas." (PMID 37066876, 2023). "In addition, a high abundance of FTH1 and FTL is found in the cellular rim of tuberculosis (TB) cavitary granulomas." (PMID 37066876, 2023).
ischemic stroke (3 papers, 2020 to 2025). A stroke disorder caused by obstruction of blood flow to the brain, due to thrombotic (local blood clot formation) or embolic (due to a blood clot or other material traveling from another site) event. "Among them, FTH1, SLC40A1, NRAS, CD82, and PTPN18 emerged as potential key targets underlying the antiferroptotic effects of acupuncture on ischemic stroke." (PMID 40552324, 2025). "Bioinformatics analysis and RT-qPCR suggested that FTH1, SLC40A1, NRAS, CD82, and PTPN18 might serve as potential key targets underlying the antiferroptotic effects of acupuncture on ischemic stroke." (PMID 40552324, 2025). "The results demonstrated that the expression levels of FTH1, SLC40A1, NRAS, CD82, CD44, and PTPN18 were upregulated in mice with ischemic stroke following acupuncture treatment." (PMID 40552324, 2025). "Electroacupuncture, a common treatment in the clinic to improve the neurological function and quality of life of ischemic stroke patients, can suppress neuronal ferroptosis by accelerating the expression of GPX4 and ferritin heavy chain 1 (FTH1) in MCAO rats." (PMID 38026442, 2023). "Moreover, FTH1, SLC40A1, NRAS, CD82, and PTPN18 levels significantly increased after acupuncture in ischemic stroke mice." (PMID 40552324, 2025).
myocardial ischemia (3 papers, 2024 to 2025). A disorder of cardiac function caused by insufficient blood flow to the muscle tissue of the heart. "The changes in GPX4 and FTH1 protein expression in mice with myocardial ischemia/reperfusion injury was consistent with the results in cells." (PMID 38926825, 2024). "FTH1/FTL can increase iron levels through autophagic degradation, whereas a decrease in ferritin expression, especially its heavy chain, facilitates myocardial ferroptosis in myocardial ischemia/reperfusion injury." (PMID 38926825, 2024).
psoriasis (3 papers, 2022 to 2024). An autoimmune condition characterized by red, well-delineated plaques with silvery scales that are usually on the extensor surfaces and scalp. "Our analysis revealed the upregulation of 3 ferroptosis markers (Chac1, Slc40a1, Fth1) and 29 ferroptosis drivers (including Alox12B and Alox15B, which encodes 15-LOX-2) as well as downregulation of 7 ferroptosis suppressors in psoriasis." (PMID 39570671, 2024). "Similarly, the upregulation of PTGS2 and TFRC expression and decreased FTL, GPX4, and FTH1 mRNA levels were observed in psoriasis samples." (PMID 39308857, 2024). "In addition, some critical ferroptosis suppressor genes, such as GPX4, FTL, and FTH1, are expressed at high levels in the keratinocyte population in psoriasis." (PMID 35962439, 2022). "Psoriasis skin-derived S.B cells expressed GPX4, FTL, and FTH1 at high levels, whereas control skin-derived S.G & S.S cells expressed high levels of GPX4, FTH1, NR4A1, NFE2L2, and MT1G." (PMID 35962439, 2022).
sarcoidosis (3 papers, 2020 to 2022). Sarcoidosis is a multisystemic disorder of unknown cause characterized by the formation of immune granulomas in involved organs. "We also found autoAbs against antigens that were reported to be highly expressed in the granulomatous tissue of sarcoidosis patients, such as von Willebrand factor (vWF) and ferritin heavy chain 1 (FTH1)." (PMID 32046322, 2020). "However, some UIC STAR cohort key determinant genes, such as ATP6V0D1, FTH1, G6PD, HCK, and SPI1 have been previously associated with sarcoidosis in other studies." (PMID 36311769, 2022).
acute promyelocytic leukemia (2 papers, 2019 to 2022). An aggressive form of acute myeloid leukemia (AML), characterized by arrest of leukocyte differentiation at the promyelocyte stage, due to a specific chromosomal translocation t(15;17) in myeloid cells. "To further investigate the effects of Fth1/Prok2 on the immune function of neutrophils, we adopted recombinant lentiviral vector of Fth1/Prok2 shRNA and human promyelocytic leukemia (HL-60) cell-derived neutrophils." (PMID 36513690, 2022).
Arthritis (2 papers, 2023 to 2025). Inflammation of a joint. "Through our spatial transcriptomics analysis, we identified down-regulation of Ferritin (Fth1) gene expression within the PLN sinuses of TNF-Tg mice with Advanced arthritis, which was associated with accumulation of iron-laden macrophages." (PMID 37691918, 2023).
calcification (2 papers, 2016 to 2025). Process by which organic tissue becomes hardened by the physiologic deposit of calcium salts. "Fth1 was identified as a differentially expressed gene significantly upregulated in the aorta of both ApoE-/- mice (atherosclerotic calcification model) and chronic kidney disease (CKD) mice (medial calcification model)." (PMID 40810067, 2025). "In the present study, bioinformatics analysis of the GSE159832 dataset uncovered that Fth1 is a differentially expressed gene which is significantly upregulated in both ApoE-/- and CKD aortic calcification mice." (PMID 40810067, 2025).
endotoxemia (2 papers, 2019 to 2021). "On the contrary, deletion of myeloid FTH1 was protective against lipopolysaccharide-induced endotoxemia in mice." (PMID 33784251, 2021).
hand osteoarthritis (2 papers, 2023 to 2024). "Genetic predisposition toward higher expression of FTH1 mRNA significantly increased the risk of hand osteoarthritis (odds ratio = 1.07, 95% confidence interval: 1.02–1.11) among participants (n = 332 668) in UK Biobank." (PMID 37914703, 2023). "It has been consistently observed in previous investigations that there exists a positive relationship between higher FTH1 mRNA expression and a higher prevalence of hand osteoarthritis." (PMID 38753666, 2024).
Hepatic fibrosis (2 papers, 2021 to 2026). The presence of excessive fibrous connective tissue in the liver. "We noticed a huge increase in the expression of the ferroptosis marker ferritin heavy chain 1 (FTH1) in both clinical samples and mouse liver fibrosis." (PMID 34864819, 2021).
injury (2 papers, 2025 to 2026). Damage inflicted on the body as the direct or indirect result of an external force, with or without disruption of structural continuity. "In this study, we demonstrate that both FTH1 and FTL are significantly enriched in the serum, blood monocytes, and alveolar macrophages (AMs) of individuals with ARDS, a phenomenon we successfully replicate in a murine hyperoxia-induced acute lung injury (HALI) model." (PMID 41542049, 2026).
lymph node metastasis (2 papers, 2021 to 2023). "Simultaneously, we found that the high expression of FTH1 correlated with lymph node metastasis and higher pathological grade and clinical stage can act as an independent predictor of the poor prognosis of HNSCC." (PMID 38025726, 2023). "From the results of the stratified analysis, we guess that FTH1 expression has better prognostic value for smokers, advanced and pathologically well-differentiated patients, and its prognostic value is not affected by the status of lymph node metastasis." (PMID 38025726, 2023). "Furthermore, FTH1 mRNA levels were higher in HNSCC with lymph node metastasis than without (t = 2.764, p = 0.0060), consistent with the results of protein expression in our previous work." (PMID 34527677, 2021).
malignant glioma (2 papers, 2019 to 2022). A grade III or grade IV glioma arising from the central nervous system. "Furthermore, EZH2 is also a known regulator of Nestin expression in malignant gliomas, which we found to be decreased in PN but not MES GICs after FTH1 knockdown in our study." (PMID 31491006, 2019).
mastitis (2 papers, 2022 to 2024). Inflammation of breast tissue during lactation or postpartum due to an obstructed duct or infection. "Previous studies have shown that DEPs, such as SLC34A2, PRKCB, FTH1, and MAPK1, could be putative biomarkers for mastitis." (PMID 38731279, 2024).
mesothelioma (2 papers, 2023 to 2024). A usually malignant and aggressive neoplasm of the mesothelium which is often associated with exposure to asbestos. "In the present work, we demonstrated that, after treatments with the new prodrug, significantly lower levels of GPX4 and FTH1 were detected in mesothelioma cells, indicating the activation of ferroptosis, supporting the ultrastructural analysis." (PMID 39204360, 2024).
oral squamous cell carcinoma (2 papers, 2024). "We also detected the expression of CAV1, FTH1, and SLC3A2 in a normal oral epithelial cell line (NOK) and an oral squamous cell carcinoma epithelial cell line (HN6)." (PMID 39286654, 2024).
osteoarthritis (2 papers, 2023 to 2024). A noninflammatory degenerative joint disease occurring chiefly in older persons, characterized by degeneration of the articular cartilage, hypertrophy of bone at the margins and changes in the synovial membrane. "Though it has been extensively studied in numerous organs and diseases, the relationship between FTH1 and osteoarthritis (OA) is unclear." (PMID 38609896, 2024). "Moreover, we validated the gene (i.e., FTH1) and pathway (i.e., ferroptosis) identified by scRNA-seq through MR analysis involving 332 668 individuals from UK Biobank and a cross-sectional analysis of 1 241 participants in Xiangya Osteoarthritis Study, respectively." (PMID 37914703, 2023).
pancreatic ductal adenocarcinoma (2 papers, 2023 to 2025). An infiltrating adenocarcinoma that arises from the epithelial cells of the pancreas. "RAS mutations, including KRAS, sensitize cancer cells, including pancreatic ductal adenocarcinoma (PDAC) cells, to ferroptosis induction due to mutant RAS-mediated expression of iron metabolism genes, such as Tfrc, Fth1, and Ftl59." (PMID 37845218, 2023).
sarcoma (2 papers, 2023 to 2024). A usually aggressive malignant neoplasm of the soft tissue or bone. "To clarify the association between iron metabolism and the prognosis of sarcoma in clinical practice, we investigated the relationship between OS and the expression levels of the TFRC, FPN, and FTH1 genes in patient samples." (PMID 37444594, 2023).
varicocele (2 papers, 2020 to 2023). A condition characterized by the dilated tortuous veins of the spermatic cord with a marked left-sided predominance. "In contrast, FTH1 has been shown to be overexpressed in the unilateral varicocele group compared to the fertile group, indicating its association with male infertility." (PMID 38012716, 2023). "Nonetheless, proteins, such as CLGN, FTH1, MDH1, MIF, PPP3CA, SUCLA2, and PSMA7, involved in sperm function, apoptosis, and oxidative stress were present in a low and very low abundance in the unilateral and bilateral varicocele group, respectively." (PMID 32365753, 2020).
acute liver failure (1 paper, 2022). Rapid deterioration of liver function causing encephalopathy and coagulopathy. "We then assessed the levels of the biomarker of ferroptosis including GPX4, FTH1, and HMGB1 using a public GEO dataset (GSE74000) obtained from patients with APAP-induced acute liver failure." (PMID 35198058, 2022).
Age-related cataract (1 paper, 2024). A type of cataract (opacification of the lens) that forms during the course of aging. "A recent study reported that melatonin suppresses ferroptosis by regulating the SIRT6/p-Nrf2/GPX4 and SIRT6/NCOA4/FTH1 pathways in age-related cataract." (PMID 39519165, 2024).
autoimmune hepatitis (1 paper, 2021). Hepatitis caused by autoantibodies. "In addition, the expression of ferroptosis biomarkers (including COX2, ACSL4, and FTH1) was significantly increased in mice with S100-induced autoimmune hepatitis after specific knockdown of GPX4." (PMID 34966478, 2021). "The dysregulation of COX2, ACSL4, GPX4, and FTH1 expression, as well as MDA and iron overload levels, suggest an important role for ferroptosis in S100-induced autoimmune hepatitis." (PMID 34966478, 2021).
bacterial sepsis (1 paper, 2025). "The eight differentially expressed genes (DEGs) as key diagnostic markers for bacterial sepsis: FTH1, B2M, NAMPT, KLF6, SRGN, S100A6, S100A9, and S100A8." (PMID 41303672, 2025).
brain inflammation (1 paper, 2026). "Moreover, brain inflammation decreased iron in BMV as evidenced by an increase in the transferrin receptor and decreased FTH1, suggestive of increased iron uptake." (PMID 41871808, 2026).
breast tumor (1 paper, 2021). "Silencing IRP2 greatly retarded breast tumor growth in vivo by decreasing TfR1 expression and increasing FTH1 expression to reduce the labile iron pool." (PMID 34518441, 2021).
cataract (1 paper, 2025). Partial or complete opacity of the crystalline lens of one or both eyes that decreases visual acuity and eventually results in blindness. "Notably, we observed that advancing age was associated with a significant increase in FTH1 expression in the LECs of cataract patients, while GPX4 expression showed a corresponding decrease." (PMID 39796164, 2025). "Similar findings have been reported in severe cataract patients, where elevated FTH1 levels reflect an adaptive response rather than a protective one." (PMID 39796164, 2025).
Cerebral ischemia (1 paper, 2019). Restriction of arterial blood supply to the brain associated with insufficient oxygenation to support the metabolic requirements of the tissue. "In summary, Fth1 coupled to a shuttle plasmid (pCDH-CMV-MCS-EF1-copGFP) displays satisfactory properties for utilization as an MRI reporter gene for in vivo detection of BMSCs transplanted in response to cerebral ischemia reperfusion injury and used for therapeutic interventions." (PMID 31531004, 2019). "In addition, we could also document a marked beneficial effect of Fth1-BMSC administration; however, specifically designed studies will be necessary to further characterize the therapeutic actions of BMSCs on cerebral ischemia reperfusion injury models." (PMID 31531004, 2019).
cognitive decline (1 paper, 2025). "Herein, three cohorts of biosamples collected from subjects with ERM who had undergone phaco-vitrectomy were examined for their simultaneous expression of Reelin, in concert with Aβ1-42, FTH1 and TAU, also known as candidate hallmarks of cognitive decline (dementia and AD)." (PMID 40867631, 2025).
congenital heart disease (1 paper, 2023). A heart disease that is present at birth. "However, the specific role of FTH1 in congenital heart diseases through the ferroptosis pathway is still not fully understood, and further research is needed to unravel its involvement in these conditions." (PMID 37920788, 2023).
E. coli infection (1 paper, 2025). "In intestinal epithelial cells (IECs), E. coli infection decreases GPX4 and ferritin heavy chain 1 (FTH1) levels and increases lipid peroxidation, thereby inducing ferroptosis." (PMID 41413615, 2025). "In accordance with the in vitro findings, PTGS2 expression in BEECs increased as the duration of E. coli infection increased, whereas GPX4 expression significantly increased at 1 h post-infection, and SLC7A11, GPX4, and FTH1 expression significantly decreased at 5 h post-infection." (PMID 41413615, 2025). "E. coli infection activates GSK-3β through dephosphorylation at Ser9, active GSK-3β binds and degrades NRF2 via the proteasome pathway, and NRF2 suppression disrupts antioxidant defenses (SLC7A11/GPX4 and GCLC/GSH) and iron homeostasis (FTH1), triggering ferroptosis in BEECs." (PMID 41413615, 2025).
endometrial carcinoma (1 paper, 2022). A malignant tumor arising from the epithelium that lines the cavity of the uterine body. "In this study, after treatment of AF, the expressions of SLC7A11, GPX4, and FTH1 were upregulated, and the expression of ACSL4 was downregulated, indicating that AF induced the ferroptosis of endometrial carcinoma KLE cells." (PMID 35635082, 2022).
female infertility (1 paper, 2023). Diminished or absent ability of a female to achieve conception. "FTH1, a gene encoding ferritin heavy chain protein, has been found to be down-regulated in granulosa and cervical cells of infertile women, suggesting its potential role in female infertility." (PMID 38012716, 2023).
folic acid deficiency (1 paper, 2025). "In HT-22 cells with SLC7A11 knockdown, the expression levels of ferroptosis inhibitory proteins SLC7A11, GPX4, and FTH1 were significantly reduced, particularly under conditions of folic acid deficiency." (PMID 40724917, 2025).
gastric tumor (1 paper, 2025). "Notably, both GPX4 and FTH1 have been shown to be significantly upregulated in clinical specimens from 30 human gastric tumor cases." (PMID 40610429, 2025).
H1N1 virus infection (1 paper, 2024). "As expected, CQ significantly inhibited FTH1 degradation caused by PR8 H1N1 virus infection, which significantly accumulated at 36 hpi." (PMID 39159143, 2024). "Consistent with the results in A549 cells, the protein expression of NCOA4 and FTH1 was significantly decreased at 12, 24, and 36 hpi after HuB H1N1 virus infection." (PMID 39159143, 2024). "In NC cells, FTH1 fluorescence was significantly attenuated after PR8 H1N1 virus infection, and silencing NCOA4 significantly inhibited the attenuation of FTH1 fluorescence." (PMID 39159143, 2024). "In CQ‐treated NPTr cells, the degradation of NCOA4 and FTH1 was significantly inhibited after HuB H1N1 virus infection compared to the control." (PMID 39159143, 2024). "NCOA4 KO significantly inhibited FTH1 degradation after PR8 H1N1 virus infection." (PMID 39159143, 2024). "Western blotting showed a significant decrease in FTH1 and GPX4 protein expression levels after 24 hpi of PR8 H1N1 virus infection vs controls, which was consistent with ferroptosis characterization." (PMID 39159143, 2024).
hemochromatosis type 4 (1 paper, 2016). A form of rare hemochromatosis (HC) characterized by increased transferrin saturation and hepatocellular iron deposition with distribution patterns and clinical features indistinguishable from patients with other types of HC. "Hemochromatosis types 4 and 5 are associated with mutations of the ferroportin (Ireg 1) gene (SLC40A1, MIM #606069) and mutations of the H ferritin gene (FTH1, MIM #615517), respectively." (PMID 27363994, 2016).